IGF2 (insulin like growth factor 2)
Diseases named in the same sentence as IGF2 in open-access papers (continued):
Sharing a sentence is not in itself a finding about the gene and the disease.
tumor (724 papers, 1989 to 2026). "IGF-1 and IGF-2 secreted by tumor-associated macrophages and myofibroblasts contribute to chemoresistance in PaC by activating insulin/IGF receptors on cancer cells." (PMID 41583513, 2026). "IGF2 and its cellular functions have been implicated in primary tumor development, metastasis, immune evasion, and resistance to therapies." (PMID 41007637, 2025). "It suppresses tumor progression by promoting hnRNPK ubiquitination and inhibiting the IGF2/PI3K/AKT axis, while its loss activates immunosuppressive cancer‐associated fibroblasts." (PMID 41103217, 2025). "Loss of circSMEK1 elevated autocrine IGF2 in HCC promoting tumor growth, also activated AKT in cancer‐associated fibroblasts through paracrine, fostering an immunosuppressive microenvironment." (PMID 41103217, 2025). "Its downregulation has been associated with enhanced IGF2 signaling, increased cell growth, and tumor susceptibility." (PMID 41262921, 2025). "For example, two recombinant adenoviruses, Ad312-E1A and Ad315-E1A, induced replication, lysis, and apoptosis in tumor cells with IGF2 loss of imprinting, an epigenetic modification present in CRC." (PMID 41440025, 2025). "It has been proposed that cancer-associated fibroblasts are one of the sources of IGF2 and IGFBPs in the tumor microenvironment." (PMID 40522948, 2025). "In particular, BUD induces the methylation of CpG islands associated with two tumor-related genes, namely, Insulin-like Growth Factor 2 (IGF-2) and the Cellular Myelocytomatosis (c-MYC) oncogene." (PMID 40284499, 2025). "One of the infrequent causes is associated with tumor cell production of Insulin-like growth factor (IGF)-2." (PMID 38868260, 2024). "Collectively, these data suggest that CM-272 induces drug metabolic processes while impeding DNA integrity, tumor growth, and most importantly, IGF2-associated PI3K-AKT signaling of HB tumor cells." (PMID 38285887, 2024). "To validate our findings, we employed Kaplan-Meier survival curves and ROC curves to analyze the key genes associated with C2 tumor cell subtypes, including the top five transcription factors (IGF2, PRRX1, MAFB, LBX2, GATA2, MAFG)." (PMID 39896800, 2024). "This systematic review focuses on IGF‐2‐mediated hypoglycaemia, encompassing a wide range of underlying tumours." (PMID 38411039, 2024). "The C2 IGF2+ tumor subtype, linked to poor prognosis, offers a promising target for future therapies." (PMID 39896800, 2024). "We confirmed the key role of the C2 IGF2+ tumor cell subtype in HGSOC, which was significantly associated with poor prognosis and high levels of chromosomal copy number variations." (PMID 39896800, 2024). "It highlights key insights, such as tumour associations, prognostic indicators (e.g. chronic liver disease) and an 88% positivity rate for IGF2:IGF1 ratio>10." (PMID 38411039, 2024). "In situations where NICTH is linked to GIST, the tumor's production of a modified insulin-like growth factor (IGF)-2 is the underlying cause of the hypoglycemic episodes." (PMID 39219869, 2024). "In our study, we found that IGF2 deficiency substantially inhibited collagen deposition in tumor tissues, indicating a critical role for IGF2 in modulating the formation of a CAF-mediated physical barrier." (PMID 39545420, 2024). "A diverse array of anatomical and pathological tumour types has been implicated in the aetiology of IGF‐2‐mediated hypoglycaemia, with frequencies varying considerably across existing literature." (PMID 38411039, 2024). "This similarity is evidenced by the shared physiological functions of the receptors, such as in tumor-associated hypoglycemia caused by elevated levels of insulin or IGF-2 from tumor cells." (PMID 39273251, 2024). "Diagnosing paraneoplastic IGF‐2‐induced hypoglycaemia is important and time‐sensitive, as early identification of the underlying tumour permits comprehensive surgical resection." (PMID 38411039, 2024).
tumor (continued). "Multivariate logistic regression analysis identified chronic liver disease as a significant predictor of adverse outcomes, while a fibrous origin of the tumour was associated with a more favourable prognosis in patients with IGF‐2‐mediated hypoglycaemia." (PMID 38411039, 2024). "Non-islet cell tumour hypoglycemia (NICTH), typically mediated by insulin-like growth factor 2 (IGF-2), is a rare but highly morbid paraneoplastic syndrome associated with tumours of mesenchymal or epithelial origin." (PMID 38432069, 2024). "Loss of imprinting (LOI) in genes such as insulin-like growth factor II (IGF2) gene was reported to increase the risk of CRC via increasing CRC stem cells pluripotency by promoting tumor autophagy." (PMID 37936149, 2023). "We also investigated the association between IGF2 expression levels and immune infiltration in the tumor microenvironment (TME)." (PMID 37393293, 2023). "miR-491-5p, which plays a role in cancer initiation and progression, displayed tumor-suppressing activity linked to targeting of IGF2 in a study conducted in cell lines, tissues and plasma from CRC patients." (PMID 37371750, 2023). "Given its role in clearing IGF-2, IGF-2R functions as a tumor suppressor, where the loss of its function can lead to an accumulation of IGF-2, promoting tumorigenesis." (PMID 37834454, 2023). "Some of its targets, notably VEGF (Vascular Endothelial Growth Factor), EPO (Erythropoietin) and IGF2 (Insulin Like Growth Factor 2), have been implicated in tumor-induced angiogenesis." (PMID 37542119, 2023). "We further confirmed that IGF2 expression was associated with tumor cell migration, proliferation, and invasion in EC cells." (PMID 37393293, 2023). "It is most often caused by tumor secretion of precursor insulin-like growth factor-2 (IGF-2) which, in high concentrations, binds to insulin receptors exerting insulin-like metabolic effects." (PMID 37909001, 2023). "It is accurate to say that increased levels of insulin, IGF-1, and IGF-2 in the blood circulation are directly linked to the onset and spread of the majority of tumours." (PMID 36890832, 2023). "BWS, which is caused by increased expression of IGF-2, is mainly characterized by macroglossia, abdominal wall defects, overgrowth, an increased risk of neonatal hypoglycemia, and childhood neoplasms." (PMID 36358907, 2022). "Loss of IGF2/H19 imprinting is an early oncogenic event that is detected in tumor-paired adjacent normal tissues." (PMID 36231092, 2022). "In these tumors, the same abnormality also identified in lymphocytes was present and the level of H19/IGF2:IG DMR methylation was greater in the tumor, suggesting a causative role of the GOM in driving oncogenesis." (PMID 35804856, 2022). "Remarkably, by just probing tumor mutation landscape, we cannot assess IGF2 downregulation, but, at this juncture, sc-RNA seq of CTC proved to be an outstanding tool in detecting non-mutated genomic aberrations like overexpression of IGF2." (PMID 35163329, 2022). "By comparing RNA sequencing of isiPI3K-sensitive tumor cells and their corresponding isiPI3K-acquired-resistant tumor cells, we found that overexpression of insulin growth factor 2 (IGF2) is associated with the resistance phenotype." (PMID 34067117, 2021). "The IGF-2R/M6PR, which is considered to act as a tumor growth suppressor, has two forms: a membrane-associated and a soluble one, both of which interact with several ligands, including IGF-2, TGFβ and lysosomal enzymes." (PMID 33946484, 2021). "When stratified by tumor stage, we found that genes mutated in the IGF2/PI3K pathway occurred more frequently in stages 2 and 3 compared to stage 1 tumors (OR = 1.48, p-value 7.0 × 10−3)." (PMID 32686686, 2020). "In fact, IGF-2 was reported to increase in tumor-bearing livers of mice subjected to a choline-deficient diet and CCl4 treatment." (PMID 32486073, 2020).
tumor (continued). "TGCTs frequently retain this loss of imprinting, expressing IGF2 biallelically, which has been linked to increased tumour aggressiveness in other cancer types." (PMID 31179642, 2019). "In conclusion, high tumor IGF2 expression is an independent risk factor for reduced PFS and OS in UCS." (PMID 29455465, 2018). "We also found that black women had higher tumor epithelial IGF2 expression compared to white women, and that high IGF2 was independently associated with worse survival in black women." (PMID 29455465, 2018). "Black women have elevated tumor IGF2 compared with white women, and decreased survival associated with high IGF2." (PMID 29455465, 2018). "Alternatively, the cancer-associated stromal cells, located in the tumor microenvironment, can produce IGF-2, thus activating IR-A in a paracrine way." (PMID 30513575, 2018). "Although deregulation of IGF pathway through amplification or overexpression of IGF2 is involved in another mucosal-origin tumor, CRC, clinical relevance of IGF2R mutations is still controversial." (PMID 30373548, 2018). "The activated IGF-2/IR-A loop has been associated with tumor aggressiveness, loss of differentiation, and the acquisition of a stem-like phenotype." (PMID 30513575, 2018). "CRIS-D groups a subset of tumours enriched for IGF2 overexpression, which has been recently implicated in desensitization to EGFR blockade in patients with KRAS wild-type tumours." (PMID 28561063, 2017). "SUZ12 is downregulated in the IGF2 loss of imprinting (LOI) tumor cell lines as compared with that in the IGF2 maintenance of imprinting (MOI) tumor cell lines." (PMID 27486969, 2017). "Although loss of IGF2 imprinting has been extensively reported in a variety of human malignancies, the molecular mechanisms underlying this tumor-specific dysregulation remain to be elucidated." (PMID 27486969, 2017). "IGF2 LOI (n=13) was associated with a higher risk for loss of MTMR7 in the tumor (OR: 13.71, *p= 0.0157) compared with the control group of CRC cases with neither IGF2 LOI nor T2DM (n=16)." (PMID 27409167, 2016). "At least from the tumor cell perspective, an Igf2-Akt axis has been implicated in experimental mouse models." (PMID 27255663, 2016). "Over-production of the growth factor promotes the malignant behavior of tumor cells through enhanced cell growth and CSC self-renewal, and loss of IGF2 imprinting (LOI) is associated with tumor initiation." (PMID 27275535, 2016). "Further in vivo studies demonstrated that the stable overexpression of miR-663b or knock-down of HOTAIR inhibited tumor growth and was associated with IGF2 expression." (PMID 27895308, 2016). "To assess the association of elevated IGF-2 with a specific tumor subtype, we evaluated IGF-2 expression levels in epithelial and neighboring stromal components of ERα-positive (ER+), ERα-negative (ER−), and TNBC tumors." (PMID 25874233, 2015). "In support of the supposition, our data using paraffin-embedded tissues from HNSCC patients in a cixutumumab clinical trial showed significant increases in tumour-associated macrophages, cancer-associated fibroblasts, VE cells and IGF-2 expression." (PMID 26465273, 2015). "A number of studies have observed loss of imprinting (LOI) of IGF2 in both tumor tissues and tumor cell lines." (PMID 23900345, 2013). "The data implicating IGF-1 and IGF-2 in cancer risk and tumor progression have positioned IGF1R as a prime oncolgy therapeutic target, anticipated to have activity against a number of human malignancies." (PMID 23383308, 2013). "In the present study, we examined the effects of enhancer-DMD-H19 promoter-driven E1A expression on the growth of tumor cells based on loss of imprinting of IGF2 gene." (PMID 23900345, 2013). "In turn, over-expression of Lin28b, IGF2BP2, and IGF2 in patients’ tumours at the time of diagnosis was all associated with a higher risk of relapse." (PMID 23482325, 2012).
tumor (continued). "Expression of integrin α11β1 on tumor-associated fibroblasts has a tumor-promoting effect, because it upregulates the expression of insulin-like growth factor 2 (IGF2), which is another example of integrin-regulated growth factor signaling." (PMID 21941547, 2012). "IGF-2R, also mannose-6-phosphate receptor, is considered a tumor suppressor because it clears IGF-2 from the cell surface to attenuate signaling and loss of function mutations in IGF-2R has been identified in human cancers." (PMID 23071652, 2012). "Here we find IGF-2 as tumor-associated key node, whose location reflects both a greater importance for tumor TFs as well as increased expression in the tumor state (red dot)." (PMID 21464922, 2011). "The IGF type 1 receptor (IGF-IR) pathway, initiated by the ligands IGF-1 and IGF-2, is associated with cellular mitogenesis, angiogenesis, tumour cell survival, and tumourigenesis in various tumour cell lines." (PMID 20628389, 2010). "It is possible that DMR0 hypomethylation is associated with a more sustained activation of IGF2 in tumour cells as a result of alternative high level chromatin conformation promoted by tumour-specific activators." (PMID 18365005, 2008). "Expression of the Igf2 gene is frequently elevated in common childhood and adult neoplasms and has been associated with tumour progression and metastasis." (PMID 15333144, 2004). "Future criteria for IGF-2 staining significance could be established by including a range of control samples to reach a threshold of positivity and associated tumor pathology with IGF-2 production." (PMID 40270996, 2025). "It is caused by tumour secretion of insulin-like growth factor 2 (IGF-2)." (PMID 39931615, 2025). "Notably, a distinct cluster of IGF2+ myofibroblasts was exclusive to the metastatic cohort, hinting at a potential association with tumor progression." (PMID 39528470, 2024). "Furthermore, the interaction between fibroblast-derived CXCL12 and CXCR4 on tumor cells and monocytes also decreased notably following IGF2 loss." (PMID 39545420, 2024). "The discovery that IGF2 blockade hinders immune evasion and tumor growth prompted an investigation into whether IGF2 deficiency could potentiate the antitumor response provoked by ICB." (PMID 39545420, 2024). "The mechanisms underlying NICTH may involve tumor secretion of insulin, replacement of hepatic tissue, increased glucose utilization by the tumor, or, most commonly, secretion of IGF-2." (PMID 38868260, 2024). "Notably, we identified a significant association between the C2 IGF2+ tumor cell subtype and stage IIIC tissue, suggesting a pivotal role for this subtype in HGSOC." (PMID 39896800, 2024). "Furthermore, structural alterations (rearrangements and deletions) in tumor DNA at 11p15 are a frequent finding and can cause loss of imprinted H19 tumor suppressor gene and overexpression of the IGF2 oncogene." (PMID 38108848, 2024). "Interestingly, tumor-derived IGF2 has been implicated not only in educating cells of the primary tumor microenvironment but also in shaping the metastatic macroenvironment by stimulating the formation of pre-metastatic niches." (PMID 36672737, 2023). "In addition, the results from the GEO and TCGA tumor tissue datasets also supported the association between IGF2 hypermethylation and the risk of developing CRC." (PMID 37213278, 2023). "In addition to CAFs, other cells of the TME produced significant amounts of IGFs, especially IGF2, such as M2-like tumor-associated macrophages (TAMs)." (PMID 36672737, 2023). "Thus, the association of imprinted genes (e.g., CDKN1C, IGF2) with growth and tumor risk is emerging." (PMID 37440461, 2023). "An important aspect of BWS diagnostics is childhood tumor prediction since imprinting aberrations in the imprinting center IC1 (also called the H19/IGF2 Differentially Methylated Region, DMR) are associated with high tumor risk whilst those in IC2 (KCNQ1OT1 DMR) are not." (PMID 35860466, 2022).
tumor (continued). "The characterization of patients with either epigenetic or genetic defects altering IGF2 expression has confirmed the central role of IGF-II in human growth regulation, particularly before birth, and its effects on broader body functions, such as metabolism or tumor susceptibility." (PMID 35741015, 2022). "Actually, our recent study has reported that BCOR, a main component of PRC1.1 is frequently mutated in human MBSHHs; its deletion increases Igf2 transcriptional activation via histone H2A modification, causing enhanced tumor progression in SHH-driven murine tumors." (PMID 35573667, 2022). "Tumor-associated macrophages are known to secrete IGF-1/IGF-2 in the tumor microenvironment." (PMID 35008602, 2021). "Epigenetic modifications cause IGF2 over production in tumor cells." (PMID 34440844, 2021). "Conversely, bialellic Igf2 expression caused by loss of Igf2 imprinting is observed in Beckwith-Wiedemann patients, a syndrome characterized by somatic overgrowth, neonatal hypoglycaemia with variable penetrance and increased predisposition to tumours." (PMID 33057429, 2020). "Intriguingly, deficient IGF-2 tumor cells were more sensitive to chemotherapy-induced apoptosis." (PMID 32365560, 2020). "A heterozygous stop mutation in IGF2 is present in blood and it is homozygous in the tumor." (PMID 33379206, 2020). "During stroma-cancer cells crosstalk, cancer-associated fibroblasts may secrete IGF2 to activate IGF-IR/Nanog axis in tumor cells and promote cancer stemness." (PMID 32493414, 2020). "Additionally, IGF2 is produced by tumor stromal cells including cancer associated fibroblasts (CAFs) and macrophages." (PMID 31480557, 2019). "Loss of imprinting (LOI) of IGF2 could lead to IGF2 overexpression, increased cell proliferation, and tumor development." (PMID 31623387, 2019). "It has been proposed that tumour growth promotion might result because of increased local IGF2 supply, as a result of the specific loss of IGF2 binding to IGF2R." (PMID 31388182, 2019). "In addition, IR-A activation, mainly by IGF-2, promotes metastasis and is linked to tumor progression and de-differentiation." (PMID 30453495, 2018). "In particular, the two mature sequences of miR483, miR483-5p and miR483-3p, mapping in the second intron of the insulin-like growth factor 2 (IGF2) gene, have proved to be overexpressed both in the primary tumor and the bloodstream, with a diagnostic and prognostic value." (PMID 29029450, 2017). "Indeed, reactivation of IGF2 expression on the maternal allele has been previously reported in a number of human tumors and tumor cell lines." (PMID 26116569, 2015). "IGF-2 gene is imprinted and its overexpression in neoplasia could result from the loss of imprinting." (PMID 24885964, 2014). "We explored whether this difference in IGF2 expression was associated with differences in the phenotype or tumor biology between the two groups of ACC." (PMID 25089899, 2014). "While the paternally expressed IGF2 encodes a member of the insulin family of polypeptide growth factors, which are involved in growth and development, the maternally expressed H19 encodes a non-coding RNA, and functions as a tumor suppressor." (PMID 29963333, 2014). "Finally, a CN gain at imprinted “IGF2” locus chr 11p15.5 appeared to be an early alteration in a multi-step tumor progression, followed by the loss of one or two alleles, associated with increased IGF2 expression, only in carcinomas." (PMID 24066089, 2013). "Igf2 mRNA has been implicated as a main target of Imp3, and activation of Igf2 mRNA translation driven by Imp3 was previously found resulting in modulation of cellular functions such as proliferation and tumorigenic activity as well as tumor cell invasion." (PMID 23226335, 2012).